ABCC1 (ATP binding cassette subfamily C member 1 (ABCC1 blood group))
Diseases named in the same sentence as ABCC1 in open-access papers (continued):
Sharing a sentence is not in itself a finding about the gene and the disease.
pancreatic cancer (15 papers, 2015 to 2024). "For example, MUC1 has been shown to act as a transcriptional inducer of ABCC1 in pancreatic cancer, whereas in cervical cancer, MUC1 promotes ABCB1 expression through an EGFR-dependent mechanism." (PMID 38254882, 2024). "miR-1291 is often downregulated in pancreatic cancer resulting in an increased expression of ABCC1 that finally leads to higher efflux rate of toxic substances." (PMID 29967761, 2018). "In pancreatic cancer cell lines, expression of the transporter ABCC1 is controlled by miR-1291 binding to the 3′-UTR." (PMID 29967761, 2018). "First of all, we were interested if ABCC1 hypomethylation is cancer type-specific or also occurs in other types of cancer than pancreatic cancer." (PMID 27689338, 2016). "The eight CpGs targeted by our ABCC1 method are directly upstream of the CpGs that have been found to be hypomethylated in the pancreatic cancer cell line SW1990 and its drug-resistant subline SW1990/GZ." (PMID 27689338, 2016). "In addition to NSCLC, the overexpression of ABCC1, also known as multidrug resistance protein 1 (MRP1), has been associated with breast, ovarian, prostate, colorectal, and pancreatic cancers." (PMID 38893104, 2024). "In pancreatic cancer, ABCG2, ABCC1, ABCC5, and ABCA8 have been specifically reported to be associated with gemcitabine resistance, whereas additional ABC transporters are widely expressed in chemoresistant PDAC cells." (PMID 39000545, 2024). "Methylation levels of ABCB1, ABCC1 and ABCG2 have been determined in the pancreatic cancer cell line SW1990 and its drug-resistant subline SW1990/GZ, obtained by selecting SW1990 for resistance to gemcitabine." (PMID 27689338, 2016). "Previous work investigated that chemoresistance in pancreatic cancer cells was via regulating the expressions of MDR genes including ABCB1, ABCC1, ABCC3 and ABCC5." (PMID 26709920, 2015). "We also investigated whether MRTX849-induced ABCC1 up-regulation affects the sensitivity of gemcitabine, a commonly used chemotherapy drug in the treatment of advanced NSCLC and pancreatic cancer." (PMID 39661665, 2024). "Recently, we found that CAFs promote gemcitabine resistance in pancreatic cancer via the TGF-β1/SMAD2/3 pathway and ABCC1 transactivation and revealed that epigenetic modification mechanisms drive gemcitabine resistance in PDAC via LLGL1-associated phosphorylation of ER signaling pathway components." (PMID 35264742, 2022). "In conclusion, our study described that silencing of TM4SF1 sensitized pancreatic cancer cells via downregulating ABCB1 and ABCC1 to kill by treatment with gemcitabine may be of particular translational significance." (PMID 26709920, 2015).
glioblastoma (14 papers, 2014 to 2025). The most malignant astrocytic tumor (WHO grade IV). "High levels of NRF2 sensitize temozolomide-resistant glioblastoma cells to ferroptosis via ABCC1/MRP1 upregulation." (PMID 39193375, 2024). "High levels of NRF2 lead to sensitivity in glioblastoma dependent on the expression of its proferroptotic target ATP binding cassette subfamily C member 1 (ABCC1), resulting in GSH depletion upon blockade of the Xc system by erastin." (PMID 36937406, 2023). "Altogether, our data indicate that high levels of NRF2 result in collateral sensitivity on glioblastoma via the expression of its pro-ferroptotic target ABCC1, which contributes to GSH depletion when the system xc− is blocked by Erastin." (PMID 35803910, 2022). "It was also found that miR-1268a is one of the down-regulated miRNAs in temozolomide-resistant glioblastoma cells and directly modulates ABCC1 expression." (PMID 31861937, 2019). "The effects of PLX4032 and PLX4720 on ABCC1 were investigated in the ABCC1-expressing cell lines G62 (glioblastoma) and PC3rVCR20 (prostate cancer)." (PMID 25300205, 2014). "Mechanistically, activated adenosine triphosphate binding cassette subfamily C member 1 (ABCC1)/MRP1 by Nrf2 gives rise to the phenomenon known as collateral sensitivity in glioblastoma, where MRP1 channels export GSH and GSH-bonded TMZ out of cells, bringing about higher sensitivity to ferroptosis." (PMID 39309434, 2024). "Among the glioblastoma subtypes, the expression of ABCC1 was elevated in the mesenchymal subtype." (PMID 35803910, 2022). "Altogether, our data suggest that high expression of NRF2 may result in ferroptosis sensitivity on TMZ-resistant glioblastoma through elevated levels of expression of its pro-ferroptotic target ABCC1, which contributes to GSH depletion when system xc− is blocked." (PMID 35803910, 2022).
non-small cell lung carcinoma (14 papers, 2016 to 2026). A group of at least three distinct histological types of lung cancer, including non-small cell squamous cell carcinoma, adenocarcinoma, and large cell carcinoma. "Linked to cigarette smoking, elevated ABCC1 gene expression has been observed in both non-small cell carcinoma and small-cell carcinoma lung cancers." (PMID 30655622, 2019). "miR-185-5p is also capable of modulating cisplatin chemosensitivity of human non-small cell lung cancer by targeting ABCC1." (PMID 36111773, 2023). "Exosomal circ_0076305 promoted cisplatin (DDP) resistance of non-small cell lung cancer cell (NSCLC) by enhancing ABCC1 expression." (PMID 37525158, 2023). "For example, miRNA-185-5p was shown to modulate chemosensitivity of human non-small cell lung cancer to cisplatin via targeting ABCC1." (PMID 28969047, 2017). "For example, it has been found that circ_0076305 enhances ABCC1 expression by sponging miR-186-5p, thus regulating cisplatin (CDDP) resistance in non-small cell lung cancer (NSCLC)." (PMID 35070998, 2021). "The lncRNA metastasis-associated lung adenocarcinoma transcript 1 (MALAT1) significantly upregulates MRP1/ABCC1 and MDR1/ABCB1 by activating STAT3 in a cisplatin (DDP) resistant non-small cell lung cancer cells." (PMID 32164712, 2020). "However, a recent study showed that higher levels of swiprosin-1 and ABCC1 were found in cisplatin-resistant CL1-0 cells compared with the parental cells, indicating that swiprosin-1 promoted cisplatin resistance through activating ABCC1 for drug efflux in non-small cell lung cancer." (PMID 34759279, 2021).
small cell lung carcinoma (14 papers, 2013 to 2024). Small cell lung cancer (SCLC) is a highly aggressive malignant neoplasm, accounting for 10-15% of lung cancer cases, characterized byrapid growth, and early metastasis. "ABCC1, which was originally cloned from the human small cell lung cancer cell line H69AR, is known to transport a variety of endogenous substrates, such as the antioxidant glutathione and pro-inflammatory leukotrienes." (PMID 39661665, 2024). "For example, KCNJ2 regulates the expression of MRP1/ABCC1 to regulate cell growth and chemoresistance in small-cell lung cancer." (PMID 36100894, 2022). "Multidrug resistance-related protein 1 (MRP1 or ABCC1), which is an energy-dependent transporter, was first discovered in a multidrug-resistant small-cell lung cancer cell line." (PMID 26829120, 2016). "Recently, miR-7 modulates chemoresistance of small cell lung cancer through modulating protein expression of ABCC1." (PMID 27834829, 2016). "A high incidence of ABCC1 expression in NSCLC has been reported compared to small cell lung cancer (SCLC)." (PMID 27649127, 2016). "ABCC1 is overexpressed in small cell lung carcinoma metastases at relapse after chemotherapy and is an established member of the ATP-binding cassette (ABC) transport protein family, shown to influence chemoresistance in brain, breast, liver, and prostate cancers." (PMID 29643985, 2018). "For instance, visfatin appears to lower doxorubicin sensitivity in small cell lung cancer (SCLC) A549 and H1793 cell lines by activating the Akt/ABCC1 signaling pathways." (PMID 37286356, 2023). "Thus, the strongly ABCC1- and LRP-overexpressing small cell lung cancer GLC4/ADR and the colchicine-selected, ABCB1-overexpressing, HeLa cell subclone KB-C-1, were equally sensitive against hellebrigenin as their parental cell lines." (PMID 23621895, 2013).
acute lymphoblastic leukemia (12 papers, 2014 to 2025). Leukemia with an acute onset, characterized by the presence of lymphoblasts in the bone marrow and the peripheral blood. "Their finding revealed that expression of ABCC2-6 was elevated and ABCC1 and 10 were downregulated which is associated with the progression of acute lymphoblastic leukemia." (PMID 39717760, 2024). "Lymphoblastic leukemia cells that overexpress ABCC1 spontaneously shed MPs containing ABCC1, which can then transfer to drug-sensitive cells within 12 h of co-culture." (PMID 39403600, 2024). "The polymorphism rs3743527 within the 3′ Untranslated Region (3′ UTR) of the ATP binding cassette subfamily C member 1 (ABCC1) gene in children affected by Acute Lymphoblastic Leukemia (ALL) decreased the ABCC1 expression, through a posttranscriptional mechanism, promoting ACT." (PMID 38140053, 2023). "Moreover, ABCC1 expression was found to be increased in children with acute lymphoblastic leukemia, and ABCC1 gene induction resulted in worsened disease-free and overall survival rates." (PMID 31391850, 2019). "Transmembrane transporters from the ATP Binding Cassette (ABC) superfamily ABCB1 (MDR1), ABCC1, ABCG2 are involved in the acquired resistance in AML, acute lymphocytic leukemia (ALL) and chronic myeloid leukemia (CML)." (PMID 34683897, 2021). "It has been reported that ABCC1, ABCC2, ABCC3, ABCC4, ABCC5 and ABCC6 play a significant role in MDR mediated non-small cell lung cancer (NSCLC), breast cancer, prostate cancer, colorectal cancer, ovarian cancer and acute lymphoblastic leukemia (ALL)." (PMID 25191874, 2014).
gastric cancer (12 papers, 2015 to 2025). A primary or metastatic malignant neoplasm involving the stomach. "In conclusion, our research suggests that the exosomal transfer of M2 macrophage‐derived circTEX2 enhances cisplatin resistance in gastric cancer through miR‐145/ABCC1." (PMID 38102848, 2023). "Inhibition of the circTEX2/miR‐145/ABCC1 axis blocked the cisplatin resistance of gastric cancer induced by M2 macrophages, as evidenced by in vitro and in vivo experiments." (PMID 38102848, 2023). "Classical drug-resistant molecules, such as P-glycoprotein (P-gp)/ABCB1 and multi-drug resistance protein (MRP1)/ABCC1, have been found to play important roles in mediating MDR in some gastric cancers." (PMID 25901126, 2015). "Likewise, hsa-miR-34a-5p enhanced the chemotherapy sensitivity of resistant gastric cancer cells by targeting SIRT1, ABCB1, and ABCC1." (PMID 38057687, 2024). "Moreover, knockdown of HOTAIR inhibited expression of the multidrug-resistance genes ABCB1, ABCC1, and ABCG2 in cisplatin-resistant gastric cancer cells and reduced xenograft tumor growth in nude mice." (PMID 36471329, 2022). "Results indicated that activation of the PI3K/AKT pathway by 740Y-P or SC79 in SGC7901/DDP cells with miR-95-3p knockdown induced an increase in MDR1 and ABCC1 expression, which further validated that miR-95-3p contributes to the development of DDP resistance in gastric cancer." (PMID 33714198, 2021). "Mechanistically, PUF60 enhances chemotherapy resistance in gastric cancer (GC) cells by actively excluding chemotherapy drugs via the recombinant ATP Binding Cassette Transporter A1 (ABCA1) and ATP Binding Cassette Subfamily C Member 1 (ABCC1)." (PMID 39781520, 2025).
leukemia (12 papers, 2013 to 2023). A malignant (clonal) hematologic disorder, involving hematopoietic stem cells and characterized by the presence of primitive or atypical myeloid or lymphoid cells in the bone marrow and the blood. "Together, these data show that loss of ABCC1 increases the sensitivity of leukemia cells to AZD-4320 treatment in vivo and in vitro." (PMID 37726279, 2023). "Elevated levels of ABCC1 have been reported to be associated with clinical drug resistance in several malignancies such as lung, esophageal, leukemia and childhood neuroblastoma." (PMID 36309544, 2022). "While the engraftment rates were similar between cohorts, the leukemia burden was significantly reduced in mice transplanted with MOLM-13 ABCC1-knockout cells upon AZD-4320 treatment compared to vehicle treatment and to MOLM-13 AAVS1.1 control cells." (PMID 37726279, 2023). "Inactivation of ABCC1 was sufficient to re-sensitize resistant leukemia cells to Venetoclax treatment and high ABCC1 expression predicted inferior responses to Venetoclax in AML patients." (PMID 37726279, 2023). "Based on the real-time PCR assay, 5 days of incubation with ATRA (10 μM), kaempferol, and EGCG (100 μM) decreased the expressions of ABCB1 and ABCC1 genes in leukemia HL60 cells (p<0.001)." (PMID 34290963, 2021). "T-EV-mediated intercellular transmission of effective MRP1 “drug outflow pumps” (ABCC1) has been demonstrated in leukaemia cells." (PMID 33081785, 2020). "The fact that IBR re-sensitises drug-resistant ABCC1-overexpressing leukaemia cells to DOX inspired us to investigate whether a similar interaction could be observed with ZAN." (PMID 36297430, 2022). "Similarly, extracellular vesicles-mediated intercellular transfer of functional MRP1 drug efflux transporter (ABCC1) was reported in leukemia cells." (PMID 30925923, 2019). "Genetic and pharmacologic ABCC1 inactivation potentiates the anti-leukemic effects of BCL-2 inhibitors and efficiently re-sensitizes Venetoclax-resistant leukemia cells." (PMID 37726279, 2023).
prostate carcinoma (11 papers, 2011 to 2025). A carcinoma that arises from epithelial cells of the prostate gland. "Finally, we identified known drug targets for non-cardiac diseases, including those that have been associated with adverse cardiac outcomes (for example, ABCC1 (target of abiraterone for prostate cancer) and DPP4 (target of sitagliptin for pancreatic beta cells in diabetes))." (PMID 36950336, 2023). "Once confirmed that S3 was able to inhibit ABCC1 activity, we performed a dose response analysis in additional prostate cancer cell lines and PNT2 cells." (PMID 32718079, 2020). "ABCC3 expression has been found to be very low in prostate cancer specimens while ABCC1 is upregulated." (PMID 32718079, 2020). "Our data demonstrate that pharmacological inhibition of ABCC1 reduced prostate cancer cell growth in vitro and potentiated the effects of Docetaxel in vitro and in mouse models of prostate cancer in vivo." (PMID 32718079, 2020). "Specifically, the observation that siRNA-mediated downregulation of ABCC1 significantly decreased LPI export from prostate cancer PC3 cells pointed to a central role for the transporter in this process." (PMID 32718079, 2020). "Our study further shows that targeting of ABCC1 with novel inhibitors reduces cancer cell growth in vitro and in vivo in preclinical models of prostate cancer." (PMID 32718079, 2020). "This study demonstrates that pharmacological inhibition of ABCC1 reduces prostate cancer cells growth in vitro and sensitizes them to Docetaxel treatment both in vitro and in vivo." (PMID 32718079, 2020). "Taken together, these data indicate that S3 not only reduced prostate cancer cell numbers and colony formation in soft agar, likely through inhibition of ABCC1, but it also potentiated the effect of Docetaxel in vitro." (PMID 32718079, 2020). "In this study, we investigated the effect of ABCC1 blockade on prostate cancer cell proliferation in vitro and in vivo." (PMID 32718079, 2020). "In prostate cancer, expression of ABCC1 was found to correlate with cancer stage and resistance." (PMID 37239055, 2023). "In this study, we investigated whether the blockade of ABCC1 affects prostate cancer cell proliferation using both in vitro and in vivo models." (PMID 32718079, 2020). "In addition, the combination of the two drugs strongly reduced HiMYC cell numbers and the ability of these cells to form colonies in a clonogenic assay, suggesting that ABCC1 inhibition can sensitize prostate cancer cells to the effect of Docetaxel." (PMID 32718079, 2020). "Additional work, however, is required to definitely establish whether c-MYC regulates ABCC1 protein levels in prostate cancer cells." (PMID 32718079, 2020). "In addition, NOTCH1 signalling has been shown to increase ABCC1 expression in prostate cancer stem cells." (PMID 32718079, 2020). "Collectively, these data identify ABCC1 as a novel and promising target in prostate cancer therapy." (PMID 32718079, 2020). "Notably, elevated expression of ABCC1 was detected in prostate cancer samples compared to normal tissues." (PMID 32718079, 2020). "Our group previously demonstrated that ABCC1 is involved in an autocrine loop by which prostate cancer cells can stimulate their own proliferation through the release of the lysophospholipid lysophosphatidylinositol (LPI) and activation of the G protein-coupled receptor GPR55." (PMID 32718079, 2020). "As MYC is commonly overexpressed in prostate cancer where it is recognized as an early driver of carcinogenesis, this raises the question of whether upregulation of ABCC1 might be regulated by c-MYC in prostate cancer cells." (PMID 32718079, 2020).
prostate carcinoma (continued). "The well-known role played by lipid rafts and prostasomes in signal transduction underlines the functional implications of this observation and might explain the different sensitivity to ABCC1 inhibitors that we detected in prostate cancer cells compared to PNT2 cells." (PMID 32718079, 2020). "Consistent with this, expression of both ABCC1 and GPR55 is detected in human prostate cancer cell lines PC3, DU145 and LNCaP." (PMID 32718079, 2020). "This is underlined by recent observations in prostate carcinoma cells, showing that the protein expression of ABCB1 and ABCC1 were independent of tissue oxygen levels." (PMID 22029974, 2011). "Intriguingly, data in the literature also suggest that intracellular localization rather than expression of ABCC1 might be crucial for its role in prostate cancer cells." (PMID 32718079, 2020). "This demonstrates that ABCC1, but not ABCC3, plays a key role in prostate cancer progression." (PMID 32718079, 2020).
acute myeloid leukemia (7 papers, 2019 to 2025). Acute myeloid leukemia (AML) is a group of neoplasms arising from precursor cells committed to the myeloid cell-line differentiation. "Cao and colleagues reported that ABCC1 rs212091 alleles GG and AG vs. AA had a lower risk of developing myelosuppression in Chinese acute myeloid leukemia patients." (PMID 39596349, 2024). "Disruption of GSH metabolism in acute myeloid leukemia (AML) impairs ABCC1‐mediated efflux of the BCL2 apoptosis regulator (BCL‐2) inhibitor venetoclax, thereby sensitizing malignant cells to this targeted therapy." (PMID 40919131, 2025). "Corroborating these data, it has been recently described that co-culture with mesenchymal stromal cells from bone marrow induced increased activity of ABCB1, ABCG2 and ABCC1 with the development of an SP phenotype from blasts of acute myeloid leukemias obtained from human patients." (PMID 37047018, 2023). "In acute myeloid leukemia, as well as in many other cancer types, a recognized role in affecting the initial response to chemotherapy has been attributed to the efflux pump activity of the tree most studied members of the ABC protein family, ABCB1, ABCC1, and ABCG2." (PMID 38255216, 2024).